PPIAP14 (peptidylprolyl isomerase A pseudogene 14)
Synonyms: formerly PPIP4
Gene: Transcribed processed pseudogene on chromosome 18 (5,002,759 to 5,003,254, reverse strand). Ensembl gene ENSG00000264775.
Diseases named in the same sentence as PPIAP14 in open-access papers:
PPIAP14 is named in the same sentence as 1 disease in open-access papers, as found by Europe PMC text mining. Sharing a sentence is not in itself a finding about the gene and the disease.
PPIAP14 shares sentences with these, for which no sentence is quoted: infection (1 paper).